PROX1 (prospero homeobox 1)
Diseases named in the same sentence as PROX1 in open-access papers (continued):
Sharing a sentence is not in itself a finding about the gene and the disease.
tumor (continued). "PROX1 can function either as an oncogene or as a tumor suppressor, depending on the cellular context." (PMID 36815375, 2023). "Depending on tumor types, PROX1 fulfills a dual role, acting as a tumor suppressor or tumor promoter." (PMID 36969058, 2023). "CD34, Prox-1, FLT4, and KDR are associated with endothelial cell signaling, vascularization, and angiogenesis during tumor formation." (PMID 37046832, 2023). "Collectively, these findings indicate a tumor-suppressive role of Prox1 through the direct suppression of c-Myc-induced metabolic reprogramming of cancer cells." (PMID 37508533, 2023). "PROX1 participates in cancer progression as both a tumor suppressor and an oncogene in different cancer types.PROX1 is a novel target gene that is hypermethylated and transcriptionally silenced in primary and metastatic breast cancer." (PMID 36815375, 2023). "Previous studies had shown that altered PROX1 expression in advanced malignancies is a main regulator for tumor metastases." (PMID 35342346, 2022). "Apart from staining the lymphatic tissues, PROX1 expression is also noted in tumor cells, with a nuclear or cytoplasmatic distribution, and in the tumor microenvironment." (PMID 35885529, 2022). "Tumor volumes and tumor weights were also obviously reduced in mice inoculated with PROX1 knockdown cells." (PMID 35342346, 2022). "Here, we identify Prospero-related homeobox 1 (PROX1) as a crucial factor for tumour metabolic plasticity." (PMID 36433955, 2022). "In this study, we clearly demonstrated that PROX1 is an important factor for tumour metabolic plasticity based on quantitative proteomics and biochemical and functional analyses." (PMID 36433955, 2022). "PROX1 has been used as a lymph-specific marker to identify and quantify the lymphatic vessels and investigate tumor and lymph node lymphangiogenesis." (PMID 35885529, 2022). "Another study concerning CNS tumors evaluated PROX1 expression in astrocytic gliomas of different histologic grades and revealed a positive correlation with increased tumor grade." (PMID 35885529, 2022). "Again, tumor growth was suppressed by rapamycin, and immunohistochemical analyses showed intratumoral PROX1 levels were increased by rapamycin." (PMID 35159256, 2022). "In this study, we revealed that PROX1 serves as an important factor of tumour metabolic plasticity downstream of the LKB1-AMPK axis that coordinates tumour cell anabolism during insufficient nutrient availability." (PMID 36433955, 2022). "We conducted an extensive search of the electronic database, Medline, using the keywords PROX1, tumor, pathogenesis, cancer, and prognosis." (PMID 35885529, 2022). "According to different literature reports, depending on the type of cancer, PROX1 not only work as tumor suppressor but also exhibit oncogenic activity." (PMID 35342346, 2022). "High amplification in the PROX1 mRNA score correlated significantly to LN metastasis and tumor grade." (PMID 35885529, 2022). "Taken together, these observations indicate that PROX1 inhibits BCAA metabolism in relation to tumour progression and patient survival." (PMID 36433955, 2022). "Of note, the lentivirus-mediated delivery of PROX1-S79A in the lung through nasal inhalation, resulted in a larger tumour number and increased tumour burden relative to the vector control and S79E mice." (PMID 36433955, 2022). "The meta-analysis included 1,024 patients from 5 studies to evaluate the correlation between tumor invasion depth (T1-T2 and T3-T4 groups) and PROX1 expression." (PMID 35346069, 2022). "Among them, PROX1 has exhibited important tumor-suppressing as well as tumor-enhancing properties, depending on the tumor’s organ of origin, according to the data reported by a plethora of studies." (PMID 35885529, 2022).
tumor (continued). "As expected, the levels of key enzymes implicated in BCAA metabolism were increased, and the level of p-S6K was reduced in KL tumours following Prox1 deletion compared to those derived from KL tumours." (PMID 36433955, 2022). "Depending on the specific organ affected, PROX1 has exhibited both tumor-promoting and tumor-suppressing properties, with its inhibition and reactivation representing possible novel therapeutic interventions, respectively." (PMID 35885529, 2022). "As there is no single marker that identifies lymphatic vessels specifically in human tumor tissues, we identified LECs by co-staining of Prox-1 and Podoplanin." (PMID 33868585, 2021). "Endothelial cells from different sources were mixed and assigned to four cell types, including immune EDCs (CCL5 and CXCL13), lymphatic EDCs (PDPN and PROX1), tumor EDCs (ACKR1 and POSTN), and vascular EDCs (PLVAP and SLC9A3R2)." (PMID 34697289, 2021). "PROX1 has been attributed with both oncogenic and tumor-suppressive functions in many types of human cancers." (PMID 34199763, 2021). "The specific knockdown of the Prox1 gene by in vitro RNA interference strongly reduces cell growth, whereas overexpression of Prox1 can significantly promote tumor proliferation." (PMID 34183992, 2021). "Subsequently, the exosomal LNMAT2 will be internalized by HLEC, and then promote the expression of PROX1 (prospero homeobox 1) at the epigenetic level, thus leading to lymphangiogenesis and lymph node metastasis of the tumor." (PMID 33520725, 2020). "RNA editing of the transcription factor PROX1, a candidate tumor suppressor, leads to several missense substitutions including E328G, R334G, and H536R and loses tumor suppressive functions." (PMID 33415135, 2020). "Prox1, the mammalian orthologue of Pros, is a tumour suppressor that regulates stem cell differentiation in the brain as well as many other organ systems." (PMID 32205310, 2020). "Additional reports, focusing specifically on the contribution of BMDCs of the myeloid lineage to tumor lymphangiogenesis, examined also PROX1 expression." (PMID 33071831, 2020). "On tumor sections obtained on D5 post tumor inoculation (2 days after tamoxifen delivery), the large majority of Prox1+ cells co-localized with Lyve1 and Podoplanin expressing lymphatics in the periphery of the tumor." (PMID 30604758, 2019). "Cellular localization of PROX1 however, is tumour tissue-dependent, as PROX1 can be localized in the cytoplasm, in the cell nucleus or both the cytoplasm and the nuclei." (PMID 31060342, 2019). "In eight cases that showed PROX1 downregulation in the tumor tissue, the FGF2 expression fold change was higher than PROX1." (PMID 31717665, 2019). "Subsequently, we compared the expression level of PROX1 between the tumor stages and its influence on Kaplan–Meier survival curves." (PMID 31717665, 2019). "Prospero homeobox protein 1 (PROX1), involved in the development and cell fate determination, is also expressed in malignant diseases functioning either as a tumor‐suppressing or oncogenic factor." (PMID 31560170, 2019). "Its function in cancer is context-dependent since PROX1 has been shown to play both oncogenic and tumour suppressive roles." (PMID 29934628, 2018). "The PROX1 expression was found in 25.8% (42/163) of patients with OSCC by immunohistochemistry and was markedly associated with the local progression of the tumor (T classification), clinical stage, LVD, nodal metastasis, and expression levels of FOXC2." (PMID 30115834, 2018). "Reportedly, PROX1 plays various tumor-dependent functional roles, which reflect both the oncogenic potential and a tumor-suppressive role." (PMID 30115834, 2018). "In esophageal squamous cell carcinoma cells, over-expression of PROX1 inhibits tumor cell proliferation." (PMID 28854215, 2017). "Real-time quantitative PCR (RTQ–PCR) was used to check the expression levels of LYVE–1, VEGFR–3, Podoplanin, and Prox–1 in tumor and para-cancerous tissues." (PMID 29162097, 2017).
tumor (continued). "According to this study, PROX1 facilitates tumor progression by affecting cell adhesion and polarity." (PMID 28854215, 2017). "Various levels of PROX1 protein occur in tumor cells, but the role of PROX1 in the proliferation, migration, and invasion of cancer cells is unclear." (PMID 28854215, 2017). "The positive expression rates of LYVE–1, VEGFR–3, Podoplanin, and Prox–1 in tumor tissues were 100, 93.6, 100, and 91.4%, but 100, 100, 100, and 87.2% in para-cancerous tissues." (PMID 29162097, 2017). "The effects of PROX1 expression on patient prognosis need to be further studied to determine its value as a prognostic tumor marker." (PMID 28854215, 2017). "Previous studies have indicated that PROX1 can have either tumor-suppressive or oncogenic properties." (PMID 28854215, 2017). "PROX1 overexpression correlates with increased mesenchymal phenotype, advanced tumor stage, and lymph node metastasis." (PMID 29258163, 2017). "The transcription factor Prox1, another Wnt target gene, was characterized as an oncogene: Prox1 ablation inhibited, and overexpression promoted tumor formation in ApcMin/+ mice, respectively." (PMID 27811361, 2016). "The relationship between PROX1 and cancer is complex, and PROX1 can either exhibit tumor suppressing or oncogenic properties, depending on cancer type." (PMID 27626492, 2016). "Future studies are needed to clarify the mechanisms by which PROX1 leads to tumor progression and affects clinical outcome in this patient group." (PMID 27626492, 2016). "The aim of this study was to examine tumor expression and prognostic value of PROX1 and β-catenin in PDAC." (PMID 27411302, 2016). "Univariate Kaplan-Meier model showed a statistically significant shorter survival for patients with tumors expressing high PROX1 protein (≥ 50% immunopositive tumor cells) (p = 0.009, Log-rank test)." (PMID 27626492, 2016). "Expression of Prox-1, a transcription factor expressed by lymphatic endothelial cells, was increased in the mandibular LNs draining small tumor (<10 mm2) but returned to baseline level in larger tumors (>10 mm2)." (PMID 26575174, 2015). "When specimens were stratified according to clinicopathological factors, PROX1 expression was found to be significantly related to tumor nuclear grade (P<0.001) and tumor N stage (P = 0.012)." (PMID 24797520, 2014). "In recent studies, both oncogenic and tumor-suppressive functions have been ascribed to PROX1 in a variety of different human cancers." (PMID 24797520, 2014). "Prox1 is suggested to play various tissue-dependent functional roles, which reflect both an oncogenic potential and a tumor-suppressive role." (PMID 24647631, 2014). "Given the role of PROX1 in down-regulating the E-cadherin tumor-suppressor protein, it is likely that E-cadherin is involved in PROX1-stimulated proliferation and migration of tumor cells." (PMID 24797520, 2014). "In carcinomas of the biliary system, epigenetic silencing and genomic deletions of the PROX1 gene, and the attendant drastic reduction in PROX1 protein levels, suggest that PROX1 acts as a tumor suppressor." (PMID 24797520, 2014). "To investigate if tumors with higher PROX1 expression levels also exhibited PROX1 amplification, we performed correlation analysis between amplification and expression in the same tumor samples." (PMID 25526434, 2014). "Using the Cox proportional hazard model, we tested the independent predictive value of PROX1 expression as well as other clinicopathological parameters, including age, gender, tumor diameter, T-stage, N-stage, M-stage, and nuclear grade." (PMID 24797520, 2014). "As is the case during development, the role of PROX1 in a variety of human cancer types also appears to be tissue dependent and reflect both oncogenic and tumor-suppressive potential." (PMID 24797520, 2014). "Specific staining for PROX1 was detected mainly in the cytoplasm in adjacent normal tissue; however, both cytoplasm and nuclei were PROX1 positive in tumor cells." (PMID 24797520, 2014).
tumor (continued). "In cancer, fate changes occur when factors associated with lymphatic endothelial cells such as VEGF-C and Prox1, promote tumor lymphangiogenesis by reprogramming vascular endothelial cells." (PMID 23341894, 2013). "Most samples showed PROX1 protein in <10% of the tumour cells, the remaining had between 10 and 30% or >30% immunopositive tumour cells." (PMID 21559010, 2011). "We also found some intra-tumoral variability in distribution of PROX1-positive cells, as well as a minor variation in staining intensity between different tumour cells within the same sample." (PMID 21559010, 2011). "(fibroblast growth factor receptor 3) is induced in lymphatic endothelium by its developmental "master switch" Prox1, and it plays a role in the biology of lymphatics which are important in inflammation and tumor biology." (PMID 21223544, 2011). "Low PROX1 expression was detected in 24% (122 out of 517) of the tumours, moderate in 43% (224 out of 517), strong in 20% (105 out of 517), and very strong expression in 4% (20 out of 517)." (PMID 21970873, 2011). "We found a correlation between high number of PROX1 immunopositive tumour cells and poor outcome of patients." (PMID 21559010, 2011). "There was an evident variability between the numbers of PROX1 immunopositive tumour cells in the different samples." (PMID 21559010, 2011). "High PROX1 expression was significantly more frequent in high-grade (grade 3–4) tumours when compared with low-grade (grade 1–2) tumours (P=0.0001)." (PMID 21970873, 2011). "Our results strengthen the previous preclinical observations that PROX1 has a role in tumour progression in CRC." (PMID 21970873, 2011). "The proportional distribution of PROX1 immunopositive tumour cells was found similar for all three histological groups." (PMID 21559010, 2011). "While these studies support the oncogenic roles of PROX1, many other studies demonstrate the opposing role of PROX1 as a tumor suppressor." (PMID 20730087, 2010). "Prox1 contributes to tumor progression by disrupting tissue architecture, cell polarity, and adhesion, which in the context of on-cogenic Wnt signaling leads to spatially unrestricted cell proliferation." (PMID 23675176, 2010). "Altered Prox1 mRNA expression is partly regulated by MAZ, and mutation of the prospero domain in HCC indicates an involvement for Prox1 during tumor progression." (PMID 18400094, 2008). "Prospero-related homeobox 1 (Prox1) transcription factor was described as a tumor-suppressor gene in liver tumors." (PMID 18400094, 2008). "Other researchers suggested a tumor suppressor function for Prox1 in HCC and CCC, and recently also in other tumors." (PMID 18400094, 2008). "Antibodies against human Prox-1 to visualise lymphatic vessels in tumour sections have only been used in a limited number of studies." (PMID 17117184, 2006). "Also in the central nervous system, heart, lens, retina, liver, and pancreas.Various investigations have found that PROX1 not only serves as a tumor suppressor but also has oncogenic activity depending on the kind of cancer." (PMID 40660330, 2025). "PROX1 exhibited nuclear and cytoplasmic reactions in tumor cells." (PMID 40660330, 2025). "Then, we proved that inhibiting the expression of GSK3B could suppress the phosphorylation of β-catenin and promote the transcription of PROX1, thus leading to tumor lymphangiogenesis." (PMID 39866224, 2025). "In the current study, PROX1 showed both nuclear and cytoplasmic reactions in tumor cells." (PMID 40660330, 2025). "More importantly, we found PROX1 was highly expressed in peri-tumor tissues." (PMID 40611320, 2025). "Ιn a previous comprehensive review, we highlighted the multifaceted and often contradictory roles of PROX1 in neoplasia, emphasizing its regulation of pathways like Wnt/β-catenin, Notch, and VEGF-C/VEGFR-3, which are critical to lymphangiogenesis, tumor progression, and immune evasion." (PMID 40843762, 2025).
tumor (continued). "Observations indicate a marked decrease in Prox1 expression across several gastrointestinal tumors, like liver cancer and pancreatic cancer, with the degree of reduction correlating significantly with the differentiation status of the tumor." (PMID 40909948, 2025). "Furthermore, overexpression of Prox1 was found to inhibit tumor cell proliferation in ESCC, demonstrating its role as an antitumor factor." (PMID 40909948, 2025). "Recent evidence suggests that lymphatic vascular biomarkers such as the Vascular Endothelial Growth Factor (VEGF)-R3, LYVE-1, podoplanin, and Prox-1 (prospero-related homeobox-1) play crucial roles in promoting lymphangiogenesis and facilitating tumor dissemination to axillary lymph nodes." (PMID 40647432, 2025). "In summary, PROX1 plays a multifaceted role in lymphatic metastasis by regulating lymphatic endothelial cell identity, promoting lymphangiogenesis, potentially influencing tumor cell behavior, and correlating with clinical outcomes." (PMID 39328205, 2024). "PROX1 is required for the neuronal lineage identity and tumor growth." (PMID 39470735, 2024). "Additionally, the expression of EMT markers was analyzed using IHC of tumor tissue sections, and the PROX1 knockdown tumors were discovered to exhibit lower expression of vimentin and induced expression of E-cadherin." (PMID 38244581, 2024). "Dysregulation of PROX1 expression or function may disrupt lymphatic endothelial cell identity and function, potentially affecting lymphatic vessel integrity and tumor cell trafficking." (PMID 39328205, 2024). "However, the precise mechanisms by which PROX1 regulates tumor cell behavior in the context of lymphatic metastasis require further investigation." (PMID 39328205, 2024). "We found that PROX1 regulated cell proliferation and tumor growth in NEPC." (PMID 39470735, 2024). "Beyond its effects on lymphatic endothelial cells, PROX1 may also influence the behavior of tumor cells." (PMID 39328205, 2024). "To investigate the association of PROX1 and α-SMA expression with distant metastasis, we used human colon tissue samples and conducted a comparative analysis between CRC cases with lymphatic invasion or lymph node metastasis and those with a localized tumor." (PMID 38244581, 2024). "Furthermore, Western blotting confirmed lower expression of oncogenic markers, stemness markers, CAF markers (α-SMA), and PROX1 as well as lower expression of ABCG2 in the PROX1-knockdown tumor samples as compared with vector control." (PMID 38244581, 2024). "We further investigated whether PROX1 protein levels correlated with the SUVmax, which indicates the metabolic activity of tumor lesions, from these 71 CRC patients." (PMID 36594098, 2023). "Therefore, to determine the underlying mechanism of the anti-tumor activities of TPL, we examined the effect of TPL on PROX1." (PMID 36969058, 2023). "Similarly, Prox1 exerted tumor-inhibiting actions in other tissues and organs, including the nervous system, pancreas, lung, and hematological cell lines." (PMID 37508533, 2023). "Our data raise the intriguing possibility that the tumor-suppressing function of Prox1 in these tissues may be exerted by its effect on c-Myc and metabolism." (PMID 37508533, 2023). "PROX1 regulates the proliferation and differentiation of tumor cells through different transcriptional pathways, but whether PROX1 plays the role of “tumor suppressor” or “tumor promoter” is still controversial." (PMID 36969058, 2023). "We further investigated whether PROX1 inhibits lipid peroxidation and ferroptosis to promote tumor growth and tumorigenesis." (PMID 36815375, 2023). "Prospero Homeobox 1 (PROX1) is a tumor suppressor gene or oncogene in tumor types." (PMID 37803421, 2023). "In addition, PROX1 has also been found to be involved in the occurrence and development of various tumor types." (PMID 36969058, 2023).